PSEN2 (presenilin 2)
Diseases named in the same sentence as PSEN2 in open-access papers (continued):
Sharing a sentence is not in itself a finding about the gene and the disease.
Cognitive impairment (12 papers, 2015 to 2026). Abnormal cognition is characterized by deficits in thinking, reasoning, or remembering. "Several associations between CNV mutations in genes (APP, GRN, MAPT, PSEN1, PSEN2) and various domains of cognitive impairment were identified." (PMID 40725212, 2025). "PSEN2 G34S variant was reported to relate to AD and mild cognitive impairment (MCI)." (PMID 34720994, 2021). "The carrier of the “probable pathogenic” PSEN2, p.S130L variant exhibited an AAO of 45 years and rapid progression of cognitive impairment." (PMID 29692703, 2018). "Notably, PSEN2-KO mice demonstrate high-frequency oscillations and seizure-induced cognitive deficits, representing a suitably valid model of seizure-induced behavioral effects in an AD-associated genetic background." (PMID 37592944, 2023).
melanoma (9 papers, 2017 to 2025). A malignant, usually aggressive tumor composed of atypical, neoplastic melanocytes. "By machine learning algorithms, we identified 6 key CRGs (ABCC2, CA14, EGR3, FBXW7, LDHB, and PSEN2) closely associated with melanoma." (PMID 39213172, 2024). "Sirt1 stable silencing increased Mxd1 mRNA expression and led to down-regulation of MYC targets, such as Cdkn1a, Bcl2 and Psen2, whose upregulation is associated with human melanoma aggressiveness and poor prognosis." (PMID 29383100, 2017). "Psen2 encodes the protein presenilin-2, a MYC target increased in melanoma cells, whereas Mapkapk3 is a member of the p38 pathway that promotes autophagy." (PMID 32831131, 2020). "Specifically, high expression of 4 key CRGs (ABCC2, CA14, LDHB, PSEN2) was significantly correlated with poor prognosis in melanoma patients (HR>1, P<0.05), while low expression of 2 key CRGs (EGR3, FBXW7) was significantly associated with poor prognosis (HR<1, P<0.05)." (PMID 39213172, 2024). "IGF1R, RIPK1, and PSEN2 are already known to contribute to vemurafenib resistance, suggesting that our new analysis method using v reliably identified hits whose ablation can sensitize melanoma to vemurafenib." (PMID 36829149, 2023). "Compared to normal skin tissues, 4 key CRGs (ABCC2, CA14, LDHB, PSEN2) were significantly upregulated while 2 key CRGs (EGR3, FBXW7) were significantly downregulated in melanoma tissues." (PMID 39213172, 2024). "Among them, 4 key CRGs (ABCC2, CA14, LDHB, PSEN2) were significantly upregulated and 2 key CRGs (EGR3, FBXW7) were significantly downregulated in melanoma tissues." (PMID 39213172, 2024). "The Kaplan–Meier analysis showed that five upregulated genes were significantly related to both the OS and DFS of melanoma patients, including TUBB4A, PSEN2, SLC45A2, QPRT, and TRPV2." (PMID 37439014, 2023). "In our melanoma model, the expression of these genes is increased in the tumor cell lines and, as hypothesized, there was a significant reduction of Cdkn1a, Bcl2 and Psen2 expression in SIRT1-silenced 4C11+ melanoma cell line (respectively) compared to non-silenced cell lines." (PMID 29383100, 2017). "Finally, by comparing the feature genes identified by the three machine learning approaches, six common key CRGs were identified as melanoma-related key CRGs, including ABCC2, CA14, EGR3, FBXW7, LDHB, and PSEN2." (PMID 39213172, 2024). "The results indicate that, as in the human melanomas, Mitf correlated well with expression of Ctnnb1, HDAC11 and Psen2, but unlike the human tumors Myc was not correlated with Mitf." (PMID 35771179, 2022).
memory impairment (7 papers, 2019 to 2026). "PSEN2 p.H169N was detected in patient 2, a 63‐year‐old man with memory loss for 2 years and personality changes characterized by mild laziness, dependence on others, excessive sleep, and short temper for 1 year." (PMID 30549411, 2019). "In addition, the PSEN2 p.V214L variant has also been reported in many East Asian ethnic groups, with prominent memory impairment and visuospatial deficits which commonly occur between 48 and 69 years of age." (PMID 37051054, 2023). "In this study, a novel PSEN2 Val226Ala mutation in TM5 was discovered in a 59-year-old female Korean patient from the neurology outpatient clinic, who presented with symptoms of memory impairment and visual hallucinations." (PMID 39273625, 2024). "Remarkably, a known pathogenic mutation in exon 6 of PSEN2 was identified in a Korean patient with EOAD who showed memory decline at 59 years of age, followed by memory impairment, language problems, and personality changes." (PMID 31182772, 2019).
breast carcinoma (6 papers, 2013 to 2025). "Studies indicated that many individuals diagnosed with breast cancer have PSEN2 R62H and PSEN2 R71W variations, and it was shown that these PSEN2 polymorphisms might predispose to cancer formation." (PMID 36476410, 2022).
early-onset Alzheimers disease (6 papers, 2017 to 2025). A rare form of Alzheimer's disease, occurring before the age of 65. "Familial early-onset Alzheimer’s disease (FEOAD) or early-onset AD (EOAD) associated with dominant mutations in APP, PSEN1 and PSEN2 have a high penetrance for displaying many of the clinical symptoms associated with AD." (PMID 36834781, 2023).
viral infection (6 papers, 2018 to 2025). "Genetic analysis identified copy number variations (CNVs) in the APP, PSEN1, PSEN2, MAPT, and GRN genes, while viral infections (HSV-1, HSV-2, CMV, EBV, HIV, SARS-CoV-2, Hepatitis A, B, and C) and vitamin D, B12, and B9 deficiencies were measured." (PMID 40725212, 2025).
amyotrophic lateral sclerosis (5 papers, 2016 to 2025). Amyotrophic lateral sclerosis (ALS) is a neurodegenerative disease characterized by progressive muscular paralysis reflecting degeneration of motor neurons in the primary motor cortex, corticospinal tracts, brainstem and spinal cord. "Among these four variants, PSEN1 p.R269H and TARDBP p.G287S had been previously reported as causes of AD and amyotrophic lateral sclerosis (ALS), respectively, while the remaining two variants in the APP and PSEN2 genes were novel." (PMID 40813364, 2025).
diabetes (5 papers, 2021 to 2025). "Lastly, Presenilin 2 is expressed in endocrine cells, but there is insufficient data on its role and association with diabetes." (PMID 38760690, 2024). "The current diabetes model was linked to elevated APP and BACE expression as well as reduced PSEN2 expression." (PMID 38683825, 2024). "We employed quantitative NanoString neurometabolic analysis to examine expression of 99 cerebral genes, including canonical AD genes (App and Psen2), neurometabolic genes, as well as genes regulated by AAC2 in diabetes, in WT and all APP/PS1 mice." (PMID 39519239, 2024).
Down syndrome (5 papers, 2017 to 2022). "Age at onset spanned 36 years in families with the 3.4Mb APP duplication, 34 years in the APP V717I variant, 32 years in Down syndrome, 33 years in the E280A PSEN1 variant, and 29 years in the PSEN2 N141I variant." (PMID 35604690, 2022). "Genetic familial effects beyond those associated with the E4 allele have been reported with APP gene dose (trisomy 21/Down syndrome; APP duplication) as well as mutations in PSEN1, PSEN2, and APP." (PMID 29497704, 2018).
ischemia (5 papers, 2020 to 2024). A hypoperfusion of the BLOOD through an organ or tissue caused by a PATHOLOGIC CONSTRICTION or obstruction of its BLOOD VESSELS, or an absence of BLOOD CIRCULATION. "Seven days post-ischemia, the expression of the presenilin 1 gene was reduced and the presenilin 2 gene was increased." (PMID 32366028, 2020). "In this area, the expression of the presenilin 2 gene was reduced for 2–7 days post-ischemia." (PMID 32366028, 2020).
neuroblastoma (5 papers, 2012 to 2025). Neuroblastoma (NB) is the most common solid, extracranial childhood tumor. "The increase in PSEN2 expression is consistent with previous findings where human neuroblastoma cells were exposed to LDL-cholesterol." (PMID 23805206, 2013). "Likewise, overexpressing FAD mutant forms of Presenilin-2 (PS-2) in neuroblastoma cells induced apoptotic responses that were inhibited by PTX and restored by expressing a PTX-resistant variant of Gαo but not Gαi." (PMID 28197070, 2017).
ovarian carcinoma (5 papers, 2014 to 2024). A malignant neoplasm originating from the surface ovarian epithelium. "Supporting these findings, Steg and colleagues have reported increased transcript levels of stem cell pathway genes, including the Notch pathway member presenilin 2 (PSEN2), in recurrent ovarian cancer samples compared with matched primary tumors." (PMID 25366565, 2014). "Abnormal high expression of PSEN2 is considered a negative factor in the development and progression of certain cancers such as gastric cancer, glioblastoma, and ovarian cancer." (PMID 39213172, 2024).
amyloid (4 papers, 2016 to 2025). "Crenezumab was also used to immunoprecipitate endogenous Aβ from TBS-soluble PS2APP brain homogenates, an amyloidosis mouse model of AD that expresses mutant forms of hAPP (K670N/M671L) and presenilin-2 (PS2N141I)." (PMID 31787113, 2019).
colon cancer (4 papers, 2007 to 2023). "Therefore, we used EpAb2-6 to block the function of EpEX in colon cancer cells and analyzed the phosphorylation levels of HGFR, AKT, FAK, GSK3β, ERK, ADAM17, and presenilin 2 in HCT116 cells." (PMID 37543570, 2023).
depression (4 papers, 2020 to 2025). "The seven positively selected depression-associated genes we identified in the human lineage are involved in brain development (PSEN2, ANKK1, PCDH9) and immunity (STAU1 and LYRM4), as highlighted in our results." (PMID 40075226, 2025). "It has been demonstrated that PSEN2 knock-in mice exhibit severe depressive behavior, and PCDH9 and ANKK1 have also been reported as risk genes for depression." (PMID 40075226, 2025). "In the depression portrait, PSEN2 is downregulate while PSEN1 is upregulated." (PMID 33589676, 2021). "GWAS depression genes were among depression portrait genes and common genes of interest included SPRY2 and PSEN2." (PMID 33589676, 2021).
glioma (4 papers, 2021 to 2025). A benign or malignant brain and spinal cord tumor that arises from glial cells (astrocytes, oligodendrocytes, ependymal cells). "RNAi-mediated PSEN2 inhibition was found to suppress glioma cell growth and invasion by regulating Nrg1/ErbB signaling." (PMID 39213172, 2024).
lung carcinoma (4 papers, 2019 to 2024). "In lung cancer, loss of presenilin 2, which activates Notch signaling, is associated with increased iPLA2 activity and lung tumor development." (PMID 35258176, 2022). "Compared to wild-type mice and control lung cancer cells, PSEN2 knockout mice and PSEN2 knockout lung cancer cells displayed tumor suppressive effects." (PMID 39213172, 2024).
Cerebral ischemia (3 papers, 2018 to 2022). Restriction of arterial blood supply to the brain associated with insufficient oxygenation to support the metabolic requirements of the tissue. "Seven days after cerebral ischemia, gene expression of presenilin 1 was reduced, and presenilin 2 was significantly elevated." (PMID 30545070, 2018). "Thirty days after the termination of cerebral ischemia, the expression of presenilin 1 gene increased above the control value and presenilin 2 decreased below the control." (PMID 30545070, 2018). "Evidence therefore suggests that various forms of dysregulation of the APP, BACE1 and PSEN1 and PSEN2 genes are associated with individual neuronal cell responses in the CA1 and CA3 areas of the hippocampus and temporal cortex with reversible cerebral ischemia." (PMID 35741821, 2022). "Our model of brain ischemia confirmed that presenilin 2 probably played a role in the modulation of apoptosis, because neurons in the ischemic region of the CA3 began to be under the influence of generated amyloid and dysfunctional tau protein in 7–30 days after ischemia." (PMID 31713815, 2020).
dilated cardiomyopathy (3 papers, 2019 to 2023). Cardiomyopathy which is characterized by dilation and contractile dysfunction of the left and right ventricles. "Mutations of presenilin 1 (PSEN1) and presenilin 2 (PSEN2) genes associated with familial AD have been found in patients with dilated cardiomyopathy." (PMID 35019033, 2022).
epilepsy (3 papers, 2021 to 2023). A brain disorder characterized by episodes of abnormally increased neuronal discharge resulting in transient episodes of sensory or motor neurological dysfunction, or psychic dysfunction. "However, the PSEN2 protein is known to play a role in mitochondrial-dependent calcium homeostasis, which underlies normal neuronal signaling and seizures in epilepsy." (PMID 37592944, 2023). "We sought to similarly establish the ED50 for both LTG and PER in PSEN2-KO mice as both ASMs are likely to be well-tolerated and used frequently in older adults with epilepsy." (PMID 37592944, 2023). "Furthermore, the characterization of the ASM response of PSEN2-KO mice in the acute 6-Hz model closely aligns with NINDS Research Benchmarks for epilepsy to prioritize discovery for the many forms in which epilepsy presents clinically." (PMID 37592944, 2023). "Among patients with AD, the burden of epilepsy development is significantly higher for those with the inherited form of AD, which is associated with autosomal-dominant mutation of specific genes encoding the APP protein, PSEN1 and PSEN2." (PMID 34121170, 2021).
Stroke (3 papers, 2018 to 2025). Sudden impairment of blood flow to a part of the brain due to occlusion or rupture of an artery to the brain. "In concordinance with these earier studies, we discovered three prevalent PSEN2 gene variants, PSEN2 rs11405 (c.69T > C), rs6759 (c.129C > T), and rs1046240 (c.129C > T) in our stroke patient cohort." (PMID 41379817, 2025). "In the case of PSEN2 gene variants, the most common ones detected in all our stroke patients through WES are PSEN2 rs11405 (c.69T > C), PSEN2 rs6759 (c.129C > T), and PSEN2 rs1046240 (c.129C > T)." (PMID 41379817, 2025). "Furthermore, our study identified several novel and common gene variants in stroke patients through WES, including COL4A2, PSEN2, NOTCH3, and RNF2." (PMID 41379817, 2025). "Despite a family history of stroke in this patient, genetic studies did not reveal any pathogenic mutations in the APP, PSEN1 or PSEN2 genes." (PMID 29450646, 2018).
tauopathies (3 papers, 2021 to 2025). "Mutations in genes encoding amyloid precursor protein (APP), presenilin 1 (PS1) and presenilin 2 (PS2) that promote amyloidosis and/or tauopathy are closely associated with the development of familial AD (FAD)." (PMID 33557250, 2021).
cardiomyopathies (2 papers, 2019 to 2020). "For example, mutation in presenilin 1 (PSEN1) and presenilin 2 (PSEN2) are associated with cardiomyopathies." (PMID 31671574, 2019).
dementia with Lewy bodies (2 papers, 2019 to 2022). "Interestingly, PSEN2 Thr421 could have homology with PSEN1 Thr440, as PSEN1 T440del mutations were reported from patients with AD or dementia with Lewy bodies." (PMID 36362122, 2022).
pulmonary fibrosis (2 papers, 2007 to 2012). Chronic progressive interstitial lung disorder characterized by the replacement of the lung tissue by connective tissue, leading to progressive dyspnea, respiratory failure, or right heart failure. "FAD-linked mutations have also been discovered in Presenilin 2 (PS2), which is highly similar to PS1 in both sequence and structure; however, PS2 knockout mice are viable and fertile with only mild age-dependent pulmonary fibrosis and hemorrhage." (PMID 22792491, 2012). "In comparison, PSEN2 deficient mice show no alterations in brain anatomy, and only with increasing age developed mild pulmonary fibrosis." (PMID 17854491, 2007).
Seizure (2 papers, 2021 to 2023). A seizure is an intermittent abnormality of nervous system physiology characterized by a transient occurrence of signs and/or symptoms due to abnormal excessive or synchronous neuronal activity in the brain. "Presenilin 2 (PSEN2) variants evoke EOAD, and these patients experience seizures." (PMID 37592944, 2023).
acne inversa (1 paper, 2024). "Besides AD, truncation mutations in PSEN1 and PSEN2 were associated with a wide range of disease phenotypes, such as FTD, acne inversa, and acute encephalopathy." (PMID 39596030, 2024). "In addition to AD, PSEN1 or PSEN2 haploinsufficiency may be related to other phenotypes, such as acne inversa, retinitis pigmentosa, or FTD." (PMID 39596030, 2024).
Atrophy (1 paper, 2026). Any weakening or degeneration, especially through lack of use. "In the full cohort, normative expression of MAPT, PINK1, and PSEN2 predicted regional atrophy after correction for spatial autocorrelation, although none survived multiple-testing correction." (PMID 41991538, 2026).
familial disease (1 paper, 2015). "By looking at the causes of FAD, genetic analyses have indicated that mutations in APP (amyloid precursor protein), PSEN-1 (presenilin 1) or PSEN-2 (presenilin 2) genes are the cause of the different types of familial disease." (PMID 25954151, 2015).
fungal infection (1 paper, 2022). "Additionally, it implies that both PSEN1 and PSEN2 play a pivotal role in the Notch signaling pathway of the human defense system against fungal infection on the AMPs―AFPs’ axis." (PMID 35216171, 2022).
metachromatic leukodystrophy (1 paper, 2024). A rare lysosomal storage disorder characterized by intralysosomal accumulation of sulfatides in various tissues, leading to progressive deterioration of motor and neurocognitive function. "For instance, among genetic mutations linked to known hNDDs, examples include HTT gene mutation in HD, SOD1 in amyotrophic lateral sclerosis, PSEN1, PSEN2, and APP in AD, ARSA gene mutation in metachromatic leukodystrophy (MLD), and others." (PMID 39200370, 2024).
myocardial infarction (1 paper, 2024). Gross necrosis of the myocardium, as a result of interruption of the blood supply to the area, as in coronary thrombosis. "For example, mutations in the presenilin genes PSEN1 and PSEN2 associated with early familial AD are also associated with dilated cardiomyopathy (CM) and HF, while the ApoE4 has also been associated with ischemic heart disease, myocardial infarction (MI), and AS." (PMID 39452073, 2024).
synucleinopathies (1 paper, 2024). "Beyond known PD genes GBA1 and LRRK2, rare variants AD genes (CD33, CR1 and PSEN2) and Aβ toxicity modifiers involved in RhoA/actin cytoskeleton regulation (ARGHEF1, ARHGEF28, MICAL3, PASK, PKN2, PSEN2) were shared risk factors across synucleinopathies." (PMID 38496508, 2024).
infection (45 papers, 2006 to 2025). The state of being infected such as from the introduction of a foreign agent such as serum, vaccine, antigenic substance or organism. "To investigate the effect of AD-linked mutations on the pathogen infection, we extended our analysis to iPSCs derived from patients with familial AD, carrying mutations in PSEN1 (A246E) or PSEN2 (I144N)." (PMID 40661646, 2025). "The transcripts of APP, ADAM10, BACE1, and subunits of the γ-secretase complex (PSEN1, PSEN2 APH1A and NCSTN) were significantly upregulated (p < 0.05) in at least one of the 4 investigated timepoints post-infection." (PMID 30786875, 2019).